CHMP4C (charged multivesicular body protein 4C)
Description:
Probable core component of the endosomal sorting required for transport complex III (ESCRT-III) which is involved in multivesicular bodies (MVBs) formation and sorting of endosomal cargo proteins into MVBs. MVBs contain intraluminal vesicles (ILVs) that are generated by invagination and scission from the limiting membrane of the endosome and mostly are delivered to lysosomes enabling degradation of membrane proteins, such as stimulated growth factor receptors, lysosomal enzymes and lipids. The MVB pathway appears to require the sequential function of ESCRT-O, -I,-II and -III complexes. ESCRT-III proteins mostly dissociate from the invaginating membrane before the ILV is released. The ESCRT machinery also functions in topologically equivalent membrane fission events, such as the terminal stages of cytokinesis and the budding of enveloped viruses (HIV-1 and other lentiviruses). Key component of the cytokinesis checkpoint, a process required to delay abscission to prevent both premature resolution of intercellular chromosome bridges and accumulation of DNA damage: upon phosphorylation by AURKB, together with ZFYVE19/ANCHR, retains abscission-competent VPS4 (VPS4A and/or VPS4B) at the midbody ring until abscission checkpoint signaling is terminated at late cytokinesis. Deactivation of AURKB results in dephosphorylation of CHMP4C followed by its dissociation from ANCHR and VPS4 and subsequent abscission. ESCRT-III proteins are believed to mediate the necessary vesicle extrusion and/or membrane fission activities, possibly in conjunction with the AAA ATPase VPS4. Involved in HIV-1 p6- and p9-dependent virus release. CHMP4A/B/C are required for the exosomal release of SDCBP, CD63 and syndecan.
Synonyms: SHAX3; MGC22825; VPS32C; SNF7-3
Tractability: Antibody: UniProt places it where antibodies can reach, with high confidence; its Gene Ontology location is reachable by antibodies, with high confidence. PROTAC: ubiquitination databases record sites on it.
Gene: Protein-coding gene on chromosome 8 (81,732,448 to 81,759,515, forward strand). Ensembl gene ENSG00000164695.
Subcellular location: Cytoplasm, cytosol; Late endosome membrane; Midbody, Midbody ring
Subcellular location (Human Protein Atlas): Cytokinetic bridge; Microtubules
Pathways (Reactome):
Disease: Budding and maturation of HIV virion; HCMV Late Events; Translation of Replicase and Assembly of the Replication Transcription Complex
Autophagy: Late endosomal microautophagy; Macroautophagy
Cell Cycle: Sealing of the nuclear envelope (NE) by ESCRT-III
Programmed Cell Death: Pyroptosis
Vesicle-mediated transport: Endosomal Sorting Complex Required For Transport (ESCRT)
Gene Ontology:
Molecular function: protein binding; protein homodimerization activity
Biological process: autophagosome maturation; autophagy; endosome transport via multivesicular body sorting pathway; late endosome to lysosome transport; midbody abscission; mitotic cytokinesis checkpoint signaling; mitotic metaphase chromosome alignment; multivesicular body sorting pathway; negative regulation of cytokinesis; nuclear membrane reassembly; nucleus organization; plasma membrane repair; regulation of centrosome duplication; regulation of mitotic spindle assembly; ubiquitin-dependent protein catabolic process via the multivesicular body sorting pathway; viral budding from plasma membrane; viral budding via host ESCRT complex; late endosome to vacuole transport via multivesicular body sorting pathway; macroautophagy; membrane fission; multivesicular body assembly; multivesicular body-lysosome fusion; vesicle fusion with vacuole; vacuolar transport
Cellular component: amphisome membrane; autophagosome membrane; Flemming body; kinetochore; kinetochore microtubule; lysosomal membrane; midbody; multivesicular body membrane; nuclear pore; plasma membrane; cytoplasmic side of plasma membrane; cytosol; ESCRT III complex; nuclear envelope; late endosome membrane
Genetic constraint (gnomAD): Loss-of-function variants: 20 observed, 20.86 expected, observed/expected ratio (o/e) 0.96, 90% interval 0.67 to 1.39. The upper end of that interval is the gene's LOEUF score, 1.39, which puts it in group 5 of 6, group 1 being the genes least tolerant of losing a copy. Missense variants: 218 observed, 215.4 expected, observed/expected ratio (o/e) 1.01, 90% interval 0.9 to 1.13. Synonymous variants: 83 observed, 78.72 expected, observed/expected ratio (o/e) 1.05, 90% interval 0.88 to 1.26.
Homologues: Orthologues: chimpanzee CHMP4C (99% identical), macaque CHMP4C (99% identical), dog CHMP4C (88% identical), mouse Chmp4c (86% identical), pig CHMP4C (86% identical), guinea pig CHMP4C (85% identical), rabbit CHMP4C (84% identical), tropical clawed frog chmp4c (69% identical), rat Chmp4c (68% identical), zebrafish chmp4c (64% identical). Paralogues in human: CHMP4B (63% identical), CHMP4A (54% identical), CHMP4BP1 (46% identical), CHMP7 (25% identical), CHMP5 (24% identical).
Diseases named in the same sentence as CHMP4C in open-access papers:
CHMP4C is named in the same sentence as 29 diseases in open-access papers, as found by Europe PMC text mining. Sharing a sentence is not in itself a finding about the gene and the disease. The quoted sentences say what the papers report.
cervical cancer (13 papers, 2020 to 2025). A primary or metastatic malignant neoplasm involving the cervix. "Upregulation of CHMP4C has been reported in cervical cancer and it is associated with poor survival." (PMID 36196256, 2022). "CHMP4C upregulation has been confirmed in cervical cancer tissues, promoting cell proliferation, migration, and invasion." (PMID 38720781, 2024). "Increased expression of CHMP4C in cervical cancer facilitated cervical cancer cell proliferation and invasion." (PMID 37388224, 2023). "CHMP4C has been shown to have a regulatory effect in numerous tumors, including human ovarian cancer, lung cancer and cervical cancer." (PMID 37388224, 2023). "Other studies found that CHMP4C can not only promote the malignant development of cervical cancer cells, but also regulate the occurrence and progression of lung squamous cell carcinoma through the cell cycle pathway." (PMID 36685927, 2022). "GNG7, MXRA7, ASB2, and CHMP4C are also involved in the development of lung cancer, gastric cancer, colorectal cancer, and cervical cancer, respectively." (PMID 36225190, 2022). "Compared to the normal tissues, CHMP4C is up-regulated in cervical cancer and lung squamous cell carcinoma, the knockdown of CHMP4C inhibits the proliferation of the cancer cells." (PMID 36244998, 2022). "These three DE-ARGs have been reported to be associated with cancer, of which CHMP4C and FOXO1 have been shown to play an important role in the occurrence and development of cervical cancer." (PMID 33633773, 2020). "CHMP4C has also been shown to be a prognostic marker for cervical cancer." (PMID 36685927, 2022). "Moreover, CHMP4C promotes the viability and motility of cervical cancer cells by regulating epithelial-mesenchymal transition." (PMID 36686667, 2022). "Therefore, we identified 52 PRGs from the TCGA database and screened three Differentially Expressed Pyroptosis-Related Genes (DEPRGs) in the prognosis of cervical cancer: CHMP4C, GZMB, TNF." (PMID 35574296, 2022). "In a study on a cervical cancer cell line with HPV-induced oncogenic changes, elevated CHMP4C expression increased sEV secretion and metastasis, similar to findings in pancreatic cancer." (PMID 40699655, 2025).
lung cancer (11 papers, 2015 to 2025). A malignant neoplasm involving the lung. "Within lung cancer, CHMP4C disruption has been reported to increase radiosensitivity, indicating a role in mediating resistance to irradiation and highlighting its therapeutic relevance." (PMID 41180485, 2025). "Silencing CHMP4C can enhance the sensitivity of lung cancer cells to radiation by delaying the S phase of the cell cycle." (PMID 38720781, 2024). "CHMP4C affected the proliferation of lung cancer cells by cell cycle pathway in squamous cell carcinoma of the lung." (PMID 37642814, 2024). "Meanwhile, high expression of CHMP4C also increased cell viability and anti-apoptosis in lung cancer under radiation conditions." (PMID 37388224, 2023). "Among other cancers, CHMP4C was up-regulated in lung cancer and regulated tumor proliferation by modulating cell cycle progression." (PMID 37388224, 2023). "Based on this feature, CHMP4C has been proved to be unbalanced in many cancers, such as human lung cancer, ovarian cancer, prostate cancer, among others." (PMID 32406588, 2020). "We first confirm CHMP4C offers lung cancer cells radioresistance, which will provide a potential radio-therapeutic strategy for non-small cell lung cancer by disrupting CHMP4C expression." (PMID 26712741, 2015). "Furthermore, depletion of Chmp4c sensitizes a human lung cancer cell line to killing by gamma irradiation." (PMID 34943860, 2021). "Overall, despite CHMP4C is involved in abscission checkpoint and autophagy, how it serves its function in DNA damage response as well as in lung cancer formation still remains unclear." (PMID 26712741, 2015).
prostate carcinoma (6 papers, 2017 to 2025). A carcinoma that arises from epithelial cells of the prostate gland. "CHMP4C as a model gene for pyroptosis was more closely associated with prostate cancer prognosis implying prognostic value of CHMP4C in prostate cancer." (PMID 37388224, 2023). "High enrichment of CHMP4C in the urine of patients with high Gleason score prostate cancer suggested the potential of CHMP4C as a novel diagnostic marker for prostate cancer." (PMID 37388224, 2023). "Similarly, in prostate cancer, CHMP4C is associated with poor prognosis and malignant progression, suggesting its potential as a therapeutic target." (PMID 40893939, 2025). "In this study, we utilized the GEPIA2 database and the packages “survival” and “survminer” to explore the correlation of CHMP4C expression levels with prognosis to determine whether CHMP4C can be regarded as a diagnostic biomarker for prostate cancer." (PMID 37388224, 2023). "Therefore, the diagnostic, prognostic, and therapeutic value of CHMP4C in prostate cancer also deserves to be fully explored." (PMID 37388224, 2023). "All of the results reveal that CHMP4C is a potential diagnostic biomarker for prostate cancer." (PMID 37388224, 2023). "Importantly, CHMP4C is closely correlated with prostate cancer clinicopathological parameters and prognosis, indicating that CHMP4C can be used as a novel diagnostic and prognostic molecular marker for prostate cancer." (PMID 37388224, 2023). "CHMP4C is highly expressed in prostate cancer tissues and plays a role in CHMP4C cell proliferation and metastasis by regulating the cell cycle." (PMID 37388224, 2023). "Subsequently, it was demonstrated that CHMP4C was highly expressed in the prostate cancer and was related to the advances in malignant biology." (PMID 37388224, 2023). "We first performed immunohistochemical staining on prostate cancer tissues and benign prostatic hyperplasia tissues, revealing that CHMP4C was higher in prostate cancer tissues." (PMID 37388224, 2023). "Based on CHMP4C expression, a new subtype of prostate cancer was established for precision treatment." (PMID 37388224, 2023). "Then we performed qRT-PCR, Western Blotting, transwell, CCK8, wound healing assay, colony formation assay and immunohistochemistry to verify the expression of CHMP4C, carcinogenesis and potential regulatory mechanisms in prostate cancer." (PMID 37388224, 2023). "We initially used the TCGA and TIMER databases to pinpoint the high expression of CHMP4C in prostate cancer, and we then confirmed the high expression of target genes at the molecular and protein levels." (PMID 37388224, 2023). "Taken together, the findings suggested that CHMP4C was indeed correlated with prostate cancer progression and invasion." (PMID 37388224, 2023). "Our study investigated the expression and clinical prognosis of CHMP4C and explored its potential regulatory mechanism in prostate cancer." (PMID 37388224, 2023). "Based on CHMP4C expression, we established two new subtypes of prostate cancer and found that low CHMP4C expression has a better immune response while high CHMP4C expression was more sensitive to paclitaxel and 5-fluorouracil." (PMID 37388224, 2023). "In order to further investigate the possible mechanism of action of CHMP4C in prostate cancer, we performed a co-expression analysis of CHMP4C using the TCGA database." (PMID 37388224, 2023). "We found that the expression of CHMP4C is significant in prostate cancer and the high expression of CHMP4C represents a poor clinical prognosis and malignant progression of prostate cancer." (PMID 37388224, 2023). "To select appropriate cell lines for a subsequent cell functional experiment, we tested the expression of CHMP4C in six prostate cancer cell lines (RWPE-1, LnCap, 22RVI, C4-2, PC-3, DU145)." (PMID 37388224, 2023). "Next, CHMP4C expression in prostate cancer was investigated in different pathological parameters using the UALCAN database." (PMID 37388224, 2023).
prostate carcinoma (continued). "CHMP4C, a component of the endosomal sorting complex required for transport III (ESCRT-III), has been implicated in the progression of several cancers, such as pancreatic and prostate cancer." (PMID 40893939, 2025). "Future studies with larger sample sizes may clarify the role of CHMP4C in high-grade prostate cancer." (PMID 37388224, 2023). "Therefore, further research is required in the future to understand the precise mechanisms by which CHMP4C regulates the cell cycle and influences immunotherapy response in prostate cancer." (PMID 37388224, 2023). "We found that some of these genes are involved in cell cycle regulation especially CDK2 protein, suggesting that CHMP4C may affect prostate cancer progression in part by regulating the cell cycle." (PMID 37388224, 2023). "Previous studies have shown that CHMP4C is abundantly expressed as a component of extracellular vesicles in patients with high Gleason scores and as a novel signature of pyroptosis that affects the prognosis of prostate cancer patients." (PMID 37388224, 2023). "CHMP4C was shown to be hyper-expressed among most cancer types, especially prostate cancer." (PMID 37388224, 2023). "Moreover, in vitro prostate cancer cell growth, invasion, and metastasis were all considerably reduced when CHMP4C was knocked down." (PMID 37388224, 2023). "Above findings suggested to us that the high expression level of CHMP4C in prostate cancer may represent a worse prognosis after immunotherapy." (PMID 37388224, 2023). "Among them, fatty acid binding protein 5 (FABP5), Alpha-1-Microglobulin/Bikunin Precursor (AMBP), Charged Multivesicular Body Protein 4A (CHMP4A), and Charged Multivesicular Body Protein 4C (CHMP4C) were significantly differentially expressed in prostate cancer patients compared to normal samples." (PMID 38201450, 2023). "Regulation of immune function by CHMP4C may contribute to our understanding of immunotherapy in prostate cancer." (PMID 37388224, 2023). "It has been reported that CHMP4C may play an important role in aggressive prostate cancer and may be a potential therapeutic target." (PMID 36386841, 2022). "The two clusters showed significant differences in the expression of PRGs; CHMP2A, CHMP4C, CYCS, CASP6, CASP8, GPX4, and TIRAP have high expression levels in cluster B, suggesting that these genes may associate with poor prognosis in prostate cancer." (PMID 35813821, 2022). "Importantly, our subsequent GO and KEGG analysis of CHMP4C grouped differential genes revealed that CHMP4C may have been involved in the regulation of immune function in prostate cancer." (PMID 37388224, 2023). "Above results suggested that CHMP4C may act as an immunosuppressive role in prostate cancer." (PMID 37388224, 2023). "However, the role of CHMP4C in prostate cancer is rarely mentioned." (PMID 37388224, 2023). "Therefore, further validation of CHMP4C expression in prostate cancer, and whether CHMP4C affects the biological behavior of prostate cancer and the regulatory pathways involved, will help us to identify new biomarkers and new therapeutic options." (PMID 37388224, 2023). "In addition, we used qRT-PCR to compare the expression of hub genes (CHMP4C, GSDMB, NOD2, PLCG1, CYCS, GPX4) between prostate cancer cell lines (LNCap, PC3, DU-145) and the normal prostate epithelial cell line (RWPE-1)." (PMID 36386841, 2022). "GRN, AMBP, CHMP4A, CHMP4C, and CHMP2 may play important roles in aggressive prostate cancer and may be potential targets of treatment." (PMID 28211531, 2017).
bladder cancer (5 papers, 2022 to 2023). "Third, the CHMP4C was specifically expressed in bladder cancer epithelial cells." (PMID 36090967, 2022). "Based on the correlation between tumour cells, we can speculate that CHMP4C is equally reliable as a prognostic marker for bladder cancer." (PMID 36685927, 2022).
ovarian carcinoma (5 papers, 2014 to 2021). A malignant neoplasm originating from the surface ovarian epithelium. "It is worth noting that CHMP4C has been identified as a new susceptibility gene for ovarian cancer." (PMID 32406588, 2020). "Genome wide association studies identified Chmp4C as a candidate susceptibility gene contributing to an excess familial risk to epithelial ovarian cancers (EOC) and found it to be overexpressed in two epithelial ovarian cancer cell lines and in primary EOC tissues." (PMID 24641493, 2014). "Finally, the recent identification of CHMP4C variants as risk factors for ovarian cancer suggests that abscission checkpoint defects may increase the tumorigenic potential of the daughter cells." (PMID 26011858, 2015). "Moreover, already implicated in control of the cytokinesis checkpoint, cells lacking CHMP4C accumulate DNA damage and CHMP4C has been identified recently as a susceptibility locus for ovarian cancer." (PMID 28843980, 2018). "Another ESCRT-III subunit, Chmp4C, was frequently overexpressed in ovarian carcinoma tissue, and not expressed in control tissues." (PMID 24641493, 2014).
Hearing impairment (2 papers, 2023). A decreased magnitude of the sensory perception of sound. "Previous whole exome sequencing and genome-wide association studies have also linked CHMP4C to hearing impairment, suggesting it is a good candidate for further study." (PMID 37163093, 2023). "CHMP4C, which was associated with Metabolic hearing loss in the TwinsUK cohort, is expressed in the marginal and basal cells of the stria vascularis, as well as several cell types in the organ of Corti." (PMID 37163093, 2023).